EGFR (epidermal growth factor receptor)
Diseases named in the same sentence as EGFR in open-access papers (continued):
Sharing a sentence is not in itself a finding about the gene and the disease.
cancer (continued). "The Epidermal Growth Factor Receptor (EGFR) is a receptor protein involved in many types of cancers." (PMID 35954311, 2022). "Inhibition of MIF not only suppresses cancer cell proliferation, but also enhance the sensitivity of cancer cells to anticancer drugs, including EGFR-TKIs, and overcomes anticancer drug resistance." (PMID 35372081, 2022). "For instance, the EGFR signaling pathway is involved in the pathogenesis and progression of cancers by activation of either RAS/RAF/MEK/ERK or PI3K/AKT/mTOR cascade." (PMID 36176765, 2022). "Although EGFR was deemed a promising target for cancer therapy with significant clinical success in several epithelial cancers, outcomes of EGFR inhibitors including gefitinib are often unsatisfied in some patients." (PMID 35399718, 2022). "EGFR (epidermal growth factor receptor) gene is a widely studied gene in cancer, and in the last few years it has been used as a treatment target with positive results in head and neck SCC." (PMID 35326613, 2022). "The epidermal growth factor receptor (EGFR) and carbonic anhydrase (CA), two prospective cancer inhibitor targets, were used in the molecular docking studies." (PMID 35011539, 2022). "B-ASOs have a dual therapeutic potential against cancer cells: anti-EGFR inhibitory and boron carrier (10B) delivery for BNCT which we have described previously." (PMID 36499115, 2022). "Nuclear-localized EGFR is highly associated with disease progression and a worse overall survival in numerous cancers, and with enhanced resistance to anti-EGFR TKIs." (PMID 35158954, 2022). "Inhibiting PRMT5 increased the chemotherapeutic effect of cisplatin and gemcitabine, and co-treatment of PRMT5 and EGFR inhibitor significantly inhibited cancer cell growth." (PMID 36199122, 2022). "The EGFR pathway played a key role in the pathogenesis, cell proliferation, and immune evasion of cancer." (PMID 36005485, 2022). "EGFR pathway has been involved in several critical metabolic processes in cancer cells, such as biosynthesis of fatty acids and glucose catabolism." (PMID 35455961, 2022). "Agri-food by-products derivatives also impair motility, invasiveness, or EMT in different types of cancer cells, through EGFR signaling modulation." (PMID 36428610, 2022). "NIR-PIT has been used to target various cancer-specific proteins, such as epidermal growth factor receptor (EGFR) and human epidermal growth factor receptor-2 (HER2), and both have shown excellent anti-cancer effects." (PMID 35740662, 2022). "Mounting preclinical and clinical evidence supports the role of nuclear EGFR in the malignant progression of cancer and identified it as a predictor of shortened survival." (PMID 35013116, 2022). "Epidermal Growth Factor Receptor (EGFR) is a 170 kDa surface protein that is overexpressed in oral pre-cancer and cancer." (PMID 36008552, 2022). "Drug conjugate 6a with a shorter linker than in 6b (five CH2-groups vs. six CH2-groups) is equipotent to 6b at ERα but is surprisingly 100-fold more potent as EGFR inhibitor (EC50 = 2.5 nM vs. 260 nM) making 6a a more promising anti-cancer agent." (PMID 36678697, 2022). "In this study, we found stromal cell-derived EREG not only activates Akt/mTOR, MEK/ERK pathways, signaling branches downstream of EGFR, but also generates a profound impact on genome-wide expression of cancer cells." (PMID 36202915, 2022). "The in vitro cellular uptake of NCs was higher in EGFR-expressing cancer cells than in normal cells." (PMID 36291827, 2022). "Abnormal EGFR activity leads to an excess of proliferative signaling and the role of EGFR hyperactivation in cancer onset and progression has been demonstrated for different types of cancer." (PMID 35954311, 2022). "For this reason, it seems necessary to perform a longer follow-up to further study the relationships between skin ADRs and these key evaluation indicators of cancer treatment (e.g. RR & OS) in NSCLC patients under EGFR-TKI treatment." (PMID 35505288, 2022).
cancer (continued). "Since cancer cells form colonies during tumorigenesis, we next investigated the effect of EPP on the colony formation of NSCLC cells with different EGFR mutation statuses." (PMID 35408753, 2022). "Functionalized EVs demonstrated increased accumulation in target cells expressing common cancer associated markers such as CXCR4, EGFR and EpCAM both in vitro and in vivo." (PMID 35547755, 2022). "Historically, targeted therapies for EGFR/HER positive cancer treatment have focussed on upstream components of the HER signalling pathway." (PMID 35326716, 2022). "Such cancers respond well to EGFR-tyrosine kinase inhibitors (EGFR-TKIs), which target the ATP binding site of the TK domain of EGFR, blocking downstream signalling pathways such as Ras/MAPK and PI3K/Akt." (PMID 35888768, 2022). "Results for sensitivity analyses for trials targeting EGFR-positive cancers are included in the eTable and eFigure in the Supplement." (PMID 36326764, 2022). "In our study, EML with primary cancer, as well as ECOG PS and EGFR, were also significantly associated with poor prognosis in patients with NSCLC." (PMID 35948652, 2022). "EGFR is a receptor tyrosine kinase overexpressed in various types of cancers including breast, head and neck, and prostate cancers." (PMID 35468841, 2022). "Our data demonstrates the first evidence that Q276P/R326Q missense mutations show no major effects on cellular localization and activity of CD148 to inhibit cancer cell proliferation and EGFR signaling as well as to interact with its ligand TSP1." (PMID 34791835, 2022). "EGFR over-activation is observed in a vast number of cancers, so, targeting EGFR and its downstream signaling cascades are regarded as a rational and valuable approach in cancer therapy." (PMID 36568183, 2022). "Lastly, the versatility of the pretargeting approach was demonstrated by [18F]TPF capture by a series of cancer-selective bsAbs, targeting clinically relevant cancer-associated cell surface markers MSCP, PD-L1 and EGFR." (PMID 35239034, 2022). "EGFR is correlated with poor prognosis, and cancer metastasis in different cancers including HCC, and it was negatively regulated by CPEB3 in HCC." (PMID 35805200, 2022). "In many cases, abnormal EGFR activation appears to be a key element in carcinogenesis and a major driving force for cancer growth." (PMID 35801486, 2022). "This has led to the dose reduction or discontinuation of EGFR inhibitors in the treatment of cancer." (PMID 35223483, 2022). "Until now, there are many FDA-approved drugs for the treatment of cancer targeting EGFR as erlotinib I and afatinib II." (PMID 35801486, 2022). "Potential mechanisms responsible for the acquisition of sorafenib resistance include EMT, the presence of cancer stem cells, EGFR activation, and autophagy." (PMID 35211652, 2022). "Among the anti-EGFR monoclonal antibodies (cetuximab, panitumumab, nimotuzumab, and necitumumab) used in cancer treatment, cetuximab and panitumumab have been approved for the treatment of metastatic CRC (mCRC)." (PMID 36307775, 2022). "It has been revealed that the EMT pathway and related transcription factors have been confirmed to be involved in cancer progression and resistance of EGFR TKIs NSCLC patients." (PMID 36092941, 2022). "The knockdown of BIM by small interfering RNA was observed to attenuate apoptosis induced by EGFR TKIs in cancer cell lines in vitro." (PMID 36212398, 2022). "EGFR is overexpressed in several cancers and dysregulated EGFR signaling contributes to cancer metastasis and progression by promoting epithelial-to-mesenchymal transition." (PMID 35053115, 2022). "Recently, activation of NF-κB signaling has been proven to be vital for promoting resistance to EGFR-TKIs in cancers." (PMID 35049931, 2022). "In those studies, monomethyl auristatin E (MMAE) or emtansine (DM1) were conjugated to anti-EGFR and Herceptin to achieve radiation sensitization in pre-clinical cancer models." (PMID 35328459, 2022).
cancer (continued). "Our glycoproteomic results indicated that 2DG led to the changes in N-glycosylation of some well-known cancer-associated glycoproteins, including LGALS3BP, CEACAM1, and EGFR." (PMID 35897829, 2022). "EGFR is frequently overexpressed in various cancers including head and neck, non-small-cell lung, breast, and cervical and colorectal cancers, so it can be regarded as an ideal molecular target for use in cancer imaging and therapy." (PMID 35517713, 2022). "Toward this end, it is important to find strategies for effectively enhancing mechanisms of cancer cell death, including apoptosis, with EGFR-TKI treatment." (PMID 36553449, 2022). "Many covalent modifications are involved in the early feedback loop that controls EGFR signaling in cancer progression, or the attenuation of EGFR signaling achieved through internalization or degradation of activated EGFR." (PMID 35884836, 2022). "Drug-resistant phenotypes of lung malignancies show poor response to the conventional and targeted therapeutic agents, which is especially true for the EGFR-mutant cancers." (PMID 35203671, 2022). "Similar examples have been observed in cancer cells treated with epidermal growth factor receptor (EGFR) tyrosine kinase inhibitors, in Leishmania parasites, and also in mouse fibroblasts exposed to high methotrexate concentrations." (PMID 36048821, 2022). "They include platelet-derived growth factor receptor (PDFGR), epidermal growth factor receptor (EGFR) and the fibroblast growth factor receptors (FGFRs), all of which play critical roles in mammalian development and in human cancers." (PMID 36578786, 2022). "One example is the use of small molecules and antibodies to treat cancers overexpressing the epidermal growth factor receptor (EGFR)." (PMID 35890400, 2022). "Inhibition of abnormal ERK activities in these cancer cells by canertinib (an EGFR inhibitor), vemurafenib (a BRaf inhibitor), or trametinib (a MEK inhibitor) treatment abrogated their expression." (PMID 35831322, 2022). "For patients with metastatic CRC (mCRC), cetuximab (CTX), as an EGFR monoclonal antibody, is a typical anti-cancer therapeutic method to suppress cancer progression binding with traditional chemotherapy." (PMID 34991461, 2022). "The most common side effect seen in cancer patients treated with EGFR inhibitors is an acneiform rash, seen in between 50 and 100% of treated patients." (PMID 36359813, 2022). "These classes of anti-EGFR drugs currently widely used in cancer treatment include cetuximab (humanized IgG), panitumumab (human IgG2), and necitumumab (human IgG), Food and Drug Administration (FDA)-approved mABs." (PMID 36499115, 2022). "Cetuximab acts on the epidermal growth factor receptor (EGFR) and blocks the intracellular signal transduction pathway by inhibiting tyrosine kinase (TK) bound to EGFR, thereby inhibiting cancer cell proliferation and inducing apoptosis." (PMID 36091750, 2022). "EGFR is highly expressed in a variety of cancer types, including CRC, and treatment strategies often include anti-EGFR antibodies, such as cetuximab." (PMID 36613466, 2022). "In this regard, gaining a deeper fundamental understanding of cancer cell dynamics in response to EGFR-TKIs would be of great help." (PMID 36553449, 2022). "Since everolimus synergistically enhances the anti-cancer activities of two known EGFR inhibitors (erlotinib or lapatinib) in TNBC, we performed analogous studies with FC101." (PMID 36428475, 2022). "In summary, our findings reveal a role for RhoA-mediated signaling and gene expression during the outgrowth of residual EGFR-mutant cancer cells in the brain and progression of CNS metastases under osimertinib treatment." (PMID 36509758, 2022). "Our data extend the understanding of zinc’s impacts upon the EGFR and downstream cancer-relevant proteins." (PMID 35216384, 2022).
cancer (continued). "EGFR aptamer can be specifically bound to EGFR, being used as a targeting ligand for promoting the active targeting of nanosystems to cancer cells with its overexpression." (PMID 35456655, 2022). "This demonstrated that RhoB/Akt signaling plays a role in cancer cell resistance to EGFR-tyrosine kinase inhibitors." (PMID 35884561, 2022). "Aberrant activation of EGF/EGFR signaling contributes to cancer proliferation, epithelial-mesenchymal transition, and metastasis." (PMID 35502895, 2022). "Genotyping of 578 HNSCC patients and 588 cancer-free controls for 60 EGFR SNPs revealed intronic SNPs rs12535536, rs2075110, rs1253871, rs845561, and rs6970262, and synonymous SNP rs2072454 were associated with HNSCC risk among all HNSCC patients." (PMID 35409179, 2022). "Cobas® EGFR Mutation Test v2 (Roche, Basel, Switzerland) was one of the earliest tests approved by the FDA (on 1 June 2016) to detect cancer, using blood." (PMID 36009594, 2022). "In cancer types of stomach, brain, breast, endometrium and colon, increased EGFR expression levels were also detected, suggesting possibility of EGFR mutations and poor prognosis 77,78." (PMID 35069896, 2022). "Among them, small molecule EGFR-TKIs, such as Gefitinib and Erlotinib, were introduced for cancer treatment." (PMID 36568260, 2022). "We have shown that, based on the correlation between EGFR dependency (measured by EGFR knockout, DepMap) and the expression of 16 methionine metabolism genes, the cancer cell lines of 22 different origins can be divided into two major clusters." (PMID 36361596, 2022). "In KEGG, the major pathway was indicated as EGFR tyrosine inhibitor resistance, prolactin signaling pathway, and pathway in cancer." (PMID 36531045, 2022). "In this manuscript, we describe the design and synthesis of a nanocomposite containing afatinib, polypyrrole, and iron oxide (PIA-NC) to molecularly target epidermal growth factor receptor (EGFR)-overexpressing cancer cells for photothermal conversion." (PMID 36291827, 2022). "A growing body of proof suggests that oncogenic mutated epidermal growth factor receptor (EGFR) favors an MR to glycolysis, which is conceivably reversed via EGFR tyrosine-kinase inhibitors (TKIs), thereby inhibiting cancer cell growth." (PMID 35912242, 2022). "It should be pointed out that some CRC patients in this study were treated with epidermal-growth-factor receptor (EGFR)-targeting antibody Cetuximab, which inhibits cancer proliferation and decreases Mg level as well." (PMID 35720415, 2022). "Here, we found that 2D5 peptide, a STAP-2–derived peptide, blocked STAP-2–EGFR interactions and suppressed EGFR-mediated proliferation in several cancer cell lines." (PMID 36410436, 2022). "Most of the drugs highly similar to BR were enriched with anti-cancer drugs, and their known MoAs included the inhibition of epidermal growth factor receptor, RAF, MAPK/ERK Kinase, SRC, and mTOR signaling pathways." (PMID 36304143, 2022). "A xenograft mouse model demonstrated the utility of RedoxT for in vivo NIR fluorescence imaging of EGFR-positive cancer cell lines." (PMID 35213974, 2022). "ADCC process is triggered by Cetuximab, an anti EGFR antibody, which is widely used in cancer immunotherapy, including locally advanced- or recurrent/metastatic HNSCC." (PMID 36341402, 2022). "Activation of the STAT3‐dependent pathways including the STAT3/FAK/ERK pathway, STAT3/Oct‐4 pathway in various cancer cells, and the IL‐8/STAT3 pathway and EGFR/STAT3/Sox‐2 pathways in TAMs are shown to contribute to the cancer stemness." (PMID 35356799, 2022). "In particular, two famous RTKs families are classically associated with cancer: the ERBB and HGFR families, of which EGFR and cMet are the prototypes, respectively." (PMID 35448364, 2022).
cancer (continued). "The results of the present study revealed a negative correlation between the expression of DHRS7 and the transmembrane tyrosine kinase EGFR, a receptor involved in various cancers, and which has increased expression in PCa disease progression." (PMID 35804847, 2022). "The median number of previous anti-cancer treatments was three, and the previous anti-EGFR treatment most commonly administered was panitumumab (15/27, 55%), predominantly in the first line (21/27, 78%) and always in combination with a cytotoxic backbone." (PMID 35915157, 2022). "Several studies have confirmed the therapeutic efficacy of NIR-PIT targeting EGFR in in vivo models of several types of cancer, including lung cancer." (PMID 35884975, 2022). "The Met RTK exhibits such reciprocal crosstalk with several members of the human EGFR (HER) family of RTKs when amplified in cancer cells." (PMID 35249128, 2022). "The developed doxorubicin-loaded anti-EGFR nanoMIP was tested on different cancer cell lines and cytotoxicity and apoptosis were observed only in cells that over-expressed EGFR." (PMID 35225975, 2022). "Dysregulation of EGFR signaling during tumorigenesis is also responsible for drug resistance in cancer treatment." (PMID 36499115, 2022). "Recent studies show that compound 1 possesses, surprisingly, anti-cancer activity toward EGFR-TKI-resistant NSCLC cells." (PMID 35736208, 2022). "The factors capable of inducing Blimp-1 and action mechanisms in relation with EGFR are still insufficiently investigated in keratinocytes and cancer cells." (PMID 35185556, 2022). "Several protein substrates have been experimentally confirmed for DHHC20, including those involved in cellular transformation and cancer, e.g., the epidermal growth factor receptor (EGFR), as well as many proteins of enveloped viruses." (PMID 35563480, 2022). "Through the cancer-immunity cycle, immunotherapy has informed promising approaches for EGFR-mutant advanced NSCLC patients." (PMID 35935943, 2022). "Even with mounting studies that have shown that nuclear EGFR functions as a true oncogene independently on its membrane-localized counterpart, no direct evidence demonstrate it can lead to tumorigenesis and/or cancer progression on its own." (PMID 35013116, 2022). "We employed the proportional odds model to identify significant drug targets and the corresponding compounds that increased the likelihood of stable disease versus progressive disease in cancer patients with the EGFR wild-type (WT) gene." (PMID 36230688, 2022). "In lung carcinoma, EGFR- or MET-expressing cancer cells exhibited an elevated glycolysis activity and increased production of lactate that induced CAFs to secrete large amounts of HGF through an NF-κB-dependent mechanism." (PMID 35814444, 2022). "The revealed interconnection between EGFR signaling and methionine metabolism in cancer cells was further utilized in the current study." (PMID 36361596, 2022). "Due to the fact that EGFR mutations are detected in 20%-40% of NSCLC and promote the progression of cancer 5, investigating this pathway and association with EMT in EGFR TKI-resistance in NSCLC has benefits in respect to those previous studies." (PMID 35154464, 2022). "EGFR in malignant tumours is thought to be a promoter of cancer cell proliferation, invasion, and metastasis." (PMID 34882994, 2022). "Together, all these factors are likely to be the reason for higher cancer cell death observed with NC treatment than with cetuximab monotherapy (EGFR inhibitor)." (PMID 35663647, 2022). "The epidermal growth factor receptor (EGFR) plays a fundamental role in carcinogenesis and progression in many cancers." (PMID 35159223, 2022).